BOP1 (BOP1 ribosomal biogenesis factor)
Description:
Component of the PeBoW complex, which is required for maturation of 28S and 5.8S ribosomal RNAs and formation of the 60S ribosome.
Synonyms: KIAA0124
Tractability: Small molecule: a structure with a bound ligand is known. PROTAC: ubiquitination databases record sites on it; its protein half-life has been measured.
Gene: Protein-coding gene on chromosome 8 (144,262,045 to 144,291,438, reverse strand). Ensembl gene ENSG00000261236.
Subcellular location: Nucleus, nucleolus; Nucleus, nucleoplasm
Subcellular location (Human Protein Atlas): Nucleoli; Nucleoli rim; Mitotic chromosome; Nucleoplasm
Pathways (Reactome):
Metabolism of RNA: Major pathway of rRNA processing in the nucleolus and cytosol
Gene Ontology:
Molecular function: protein binding; RNA binding; ribonucleoprotein complex binding
Biological process: maturation of LSU-rRNA from tricistronic rRNA transcript (SSU-rRNA, 5.8S rRNA, LSU-rRNA); regulation of cell cycle; ribosomal large subunit assembly; ribosomal large subunit biogenesis; ribosome biogenesis; rRNA processing; cell population proliferation; cleavage in ITS2 between 5.8S rRNA and LSU-rRNA of tricistronic rRNA transcript (SSU-rRNA, 5.8S rRNA, LSU-rRNA); maturation of 5.8S rRNA; maturation of 5.8S rRNA from tricistronic rRNA transcript (SSU-rRNA, 5.8S rRNA, LSU-rRNA)
Cellular component: chromosome; nucleolus; nucleoplasm; PeBoW complex; ribonucleoprotein complex; preribosome, large subunit precursor; nucleus
Genetic constraint (gnomAD): Loss-of-function variants: 54 observed, 74.16 expected, observed/expected ratio (o/e) 0.73, 90% interval 0.58 to 0.91. The synonymous counts are far from expectation, so gnomAD's model fits this gene poorly and the ratio says little. Missense variants: 1,170 observed, 1,014.3 expected, observed/expected ratio (o/e) 1.15, 90% interval 1.1 to 1.21. Synonymous variants: 566 observed, 424.47 expected, observed/expected ratio (o/e) 1.33, 90% interval 1.24 to 1.43.
Homologues: Orthologues: chimpanzee BOP1 (99% identical), macaque BOP1 (93% identical), guinea pig BOP1 (84% identical), dog BOP1 (84% identical), mouse Bop1 (83% identical), rat Bop1 (83% identical), pig BOP1 (82% identical), tropical clawed frog bop1 (67% identical), zebrafish bop1 (66% identical), Drosophila melanogaster CG5033 (50% identical), Caenorhabditis elegans Y48B6A.1 (41% identical).
Diseases named in the same sentence as BOP1 in open-access papers:
BOP1 is named in the same sentence as 46 diseases in open-access papers, as found by Europe PMC text mining. Sharing a sentence is not in itself a finding about the gene and the disease. The quoted sentences say what the papers report.
colorectal cancer (12 papers, 2014 to 2024). A primary or metastatic malignant neoplasm that affects the colon or rectum. "BOP1 is expressed at higher expression levels in colorectal cancer, which is associated with a poor patient prognosis, while BOP1 silencing mitigates tumor cell proliferation, migration, and invasion and enhances cell apoptosis." (PMID 34603446, 2021). "A dominant negative mutation in BOP1 has been associated with cell cycle arrest, whereas BOP1 overexpression in the liver and colorectal cancer cells increased their migration ability by activating the Wnt pathway." (PMID 31210846, 2019). "The BOP1 gene is known to be over-expressed in rectal cancer with 8q gain, and dosage increase of the BOP1 gene is associated with an increase of BOP1 mRNA in colorectal cancer." (PMID 26360582, 2015). "Interestingly, increased dosage of the BOP1 gene is associated with colorectal cancer and enhanced levels of BOP1 mRNA." (PMID 24526220, 2014). "In recent years, multiple studies have shown that BOP1 regulates tumorigenesis, epithelial‐to‐mesenchymal transition, migration, metastasis, and drug resistance in several tumor types, such as colorectal cancer, hepatocellular carcinoma, and melanoma." (PMID 32167616, 2020). "Another research has demonstrated that dosage increase of the BOP1 was a frequent event in colorectal carcinoma and related to cancer occurrence." (PMID 32071816, 2020). "In colorectal cancer, trypsin suppresses the proliferation of cancer cells by blocking downstream gene proliferation-1 (BOP-1)." (PMID 28423522, 2017). "Similarly, BOP1 ribosomal biogenesis factor (BOP1) was reported to promote the malignancy of colorectal cancer cells by inducing higher pAURKB at Thr 232 (active form of AURKB)." (PMID 38233848, 2024). "However, there is also evidence to suggest that BOP1 is a downstream target of the WNT/beta-catenin pathway in colorectal cancer cells, suggesting that additional studies are required to further understand the role of BOP1 in cancer stem cells." (PMID 36497066, 2022). "In colorectal cancer cells, BOP1 was identified as a target gene of the Wnt/β-catenin pathway." (PMID 33575212, 2020). "Abnormal expression of BOP1 modifies various aspects of colorectal cancer and melanoma." (PMID 33575212, 2020). "However, the role of BOP1 in the regulation of colorectal cancer cell migration and invasion is still largely unclear." (PMID 32167616, 2020). "Genes, such as BOP1, KIF11, and MMS22L, are associated with the progression of various cancers, such as colorectal cancer, gastric cancer, lung, and esophageal cancer, but these genes may be linked with the development of BRCA." (PMID 31311202, 2019). "BOP1 as Wnt/β-catenin target gene involved in induced migration, EMT, and metastasis of colorectal carcinoma." (PMID 32071816, 2020).
hepatocellular carcinoma (10 papers, 2015 to 2025). A malignant tumor that arises from hepatocytes. "BOP1 is widely recognized as an oncogene in hepatocellular carcinoma and several other cancers, where it promotes epithelial-to-mesenchymal transition (EMT) and correlates with poor prognosis across pan-cancer cohorts." (PMID 40963856, 2025). "Nonetheless, investigators detect MYC and BOP1 co-expression in hepatocellular carcinoma, and we observe MYC and BOP1 co-expression in some TNBC." (PMID 38473786, 2024). "BOP1 promotes the transformation of epithelial cells to mesenchymal cells and exerts a carcinogenic effect in hepatocellular carcinoma." (PMID 34712323, 2021). "A previous study showed that abnormal BOP1 expression was observed in hepatocellular carcinoma clinical specimens." (PMID 32167616, 2020). "BOP1 is known to play an oncogenic role in hepatocellular carcinoma by promoting epithelial-to-mesenchymal transition." (PMID 27811368, 2016). "BOP1 plays an oncogenic role in hepatocellular carcinoma by inducing epithelial-mesenchymal transition (EMT) and promoting actin cytoskeleton remodeling." (PMID 26360582, 2015). "Interestingly, BOP1 has been shown to be upregulated in patients with hepatocellular carcinoma as well as gastric cancer and that BOP1 induces EMT, which leads to higher invasiveness and metastasis potential." (PMID 36007075, 2022). "BOP1 could promote the epithelial‐to‐mesenchymal transition by stimulating actin stress fiber assembly and RhoA activation in hepatocellular carcinoma." (PMID 32167616, 2020). "Similarly, it was previously reported that BOP1 expression is related to shorter survival period in patients with prostate carcinoma, triple-negative breast cancer, gastric cancer, and hepatocellular carcinoma, and BOP1 promotes the development of these cancers." (PMID 34603446, 2021). "In addition, BOP1 was also found to affect the cell migration in hepatoma." (PMID 33510838, 2021). "Besides, BOP1 was reported to influence the epithelial mesenchymal transformation in hepatocellular carcinoma (HCC) through upregulating F-actin, c-catenin and vimentin, which was similar to our findings in the GC cell lines." (PMID 35222794, 2022). "Recently, BOP1 played an oncogenic role in the hepatocellular carcinoma (HCC) and melanoma." (PMID 35222794, 2022).
melanoma (7 papers, 2019 to 2022). A malignant, usually aggressive tumor composed of atypical, neoplastic melanocytes. "Biological functions of components of the PeBoW complex, such as Pes1 and Bop1, have been implicated in multiple types of malignant tumor progression, including breast cancer, colon cancer, liver cancer, and melanoma." (PMID 34868955, 2021). "A loss of BOP1 also resulted in acquired resistance to BRAF kinase inhibitors in melanoma by increasing MAPK signalling." (PMID 33685397, 2021). "Furthermore, a recent study reported that the expression of BOP1 protein was downregulated in melanoma patients, and that BOP1 loss was related to BRAF kinase resistance." (PMID 34603446, 2021). "Block of proliferation 1 (BOP1), which reportedly participates in 28S and 5.8S ribosomal RNA processing and 60S ribosome biogenesis, was down-regulated in patient-derived melanoma samples." (PMID 33685397, 2021). "BOP1 can promote the process of epithelial mesenchymal transformation in HCC and mediate BRAF inhibitor resistance in melanoma." (PMID 35222794, 2022). "BOP1 knockdown resulted in resistance to BRAF kinase inhibitors both in melanoma cell culture and in a melanoma mouse model." (PMID 32167616, 2020). "It has been reported that BOP1 knockdown resulted in the downregulation of the MAPK phosphatases DUSP4 and DUSP6 and further increased MAPK signaling and resistance to BRAF kinase inhibitors in melanoma." (PMID 32167616, 2020).
gastric cancer (5 papers, 2019 to 2022). A primary or metastatic malignant neoplasm involving the stomach. "In our study, we investigated for the first time the effect of block on proliferation 1 (BOP1) on gastric cancer." (PMID 35222794, 2022). "Cell viability, apoptosis, migration and invasion were investigated in gastric cancer cell lines with BOP1 silencing or overexpression." (PMID 35222794, 2022). "In summary, we have described the oncogenic role of block on proliferation 1 (BOP1) in gastric cancer and found that BOP1 promoted cell proliferation, invasion and EMT." (PMID 35222794, 2022). "In vivo and in vitro suppression of the proliferation process of gastric cancer (GC) cells resulted from BOP1 silencing." (PMID 36077339, 2022). "Taken together, previous findings in other malignancy supported our exploratory study of BOP1 function in gastric cancer." (PMID 35222794, 2022). "Higher expression of BOP1 was related to poor overall survival in patients with gastric cancer (HR, 1.27; 95% CI, 1.05-1.53; P < 0.05)." (PMID 35222794, 2022). "To further explore the role of BOP1 in the oncogenesis and metastasis in the gastric cancer, we tried to figure out some potential biological process that might be modulated by BOP1." (PMID 35222794, 2022). "Taken together, our findings suggested the oncogenesis role of BOP1 in the gastric cancer." (PMID 35222794, 2022). "Therefore, our study aimed to study the effect of BOP1 on proliferation and metastasis of gastric cancer cells and the possible downstream pathway, which could be a biomarker or therapeutic target in gastric cancer." (PMID 35222794, 2022). "Therefore, we hypothesized that BOP1 might play an important role in gastric cancer development." (PMID 35222794, 2022). "The present study demonstrated that BOP1 contributed to the development of gastric cancer by promoting proliferation, invasion and epithelial mesenchymal transformation, which could be a biomarker or therapeutic target in GC." (PMID 35222794, 2022). "However, the specific role of BOP1 in the gastric cancer has not been investigated." (PMID 35222794, 2022).
liver cancer (5 papers, 2020 to 2024). An epithelial or non-epithelial malignant neoplasm that arises from the liver. "In prior studies, BOP1 has been shown to promote liver cancer development via driving epithelial to mesenchymal transition." (PMID 33228611, 2020). "The results demonstrated the up-regulation of BOP1, CDC20, and UBE2S in liver cancer cells." (PMID 38577593, 2024). "For example, BOP1, involved in rRNA processing and gene expression, induces gastric, colorectal and liver carcinogenesis or metastasis, and correlates with the TNM staging, vascular invasion and poor disease-free survival in liver cancer." (PMID 33589575, 2021).
lung carcinoma (4 papers, 2020 to 2021). "We also used reverse transcription-quantitative polymerase chain reaction (RT-qPCR) to confirm BOP1 expression in lung cancer cell lines." (PMID 34603446, 2021). "The results indicated that BOP1 was significantly augmented in lung cancer cells compared with HBE cell." (PMID 34603446, 2021). "Finally, we validated the expression of BOP1 in lung cancer cell line and detected the influence of BOP1 on lung cancer cell migration and the expression of epithelial-mesenchymal transition- (EMT-) related genes." (PMID 34603446, 2021). "Nevertheless, it is uncertain if BOP1 plays crucial roles in other cancers, especially lung cancer." (PMID 34603446, 2021). "Furthermore, we detected the influence of BOP1 on lung cancer cell migration and epithelial-mesenchymal transition- (EMT-) related genes' expression." (PMID 34603446, 2021). "Interestingly, we found that two highly connected novel genes BYSL and BOP1 were significantly overexpressed in TCGA lung cancer tumor samples and their expression levels were obviously correlated with the survival of lung cancer patients." (PMID 34131148, 2021). "We detected the expression levels of BOP1 in lung cancer cell lines H292, H1299, A549, PC-9, and human bronchial epithelioid cell line HBE, and the results showed that BOP1 was significantly augmented in lung cancer cells compared with HBE cell." (PMID 34603446, 2021).
colon cancer (3 papers, 2019 to 2025). "Also, unlike its companion proteins, the expression of BOP1 in colon cancer cells is independent of c-myc activity." (PMID 31210846, 2019).
prostate carcinoma (3 papers, 2021 to 2022). A carcinoma that arises from epithelial cells of the prostate gland. "And it has been documented that the localization of BOP1, one of ribosome biogenesis factors, from nucleus to cytoplasm correlated with advanced disease and decreased survival in prostate cancer patients." (PMID 35264160, 2022). "BOP1 knockdown results in decreased proliferation and motility, implicating this gene in prostate cancer aggressiveness." (PMID 34572914, 2021).
atherosclerosis (2 papers, 2021 to 2023). A disease characterized by the build-up of fatty material and calcium deposition in the arterial wall resulting in partial or complete occlusion of the arterial lumen. "In the present study, the following were revealed: (i) BOP1 is highly expressed on the inside edge of the neointima in human coronary arteries with atherosclerosis and restenosis, as well as in arteries of animal neointimal hyperplasia models." (PMID 33510838, 2021). "The western blot and qRT-PCR revealed that BOP1 was highly expressed in the coronary artery with atherosclerosis (AS), or the coronary artery obtain from patients who received percutaneous coronary intervention (PCI) therapy, at the protein and mRNA level." (PMID 33510838, 2021). "Therefore, increased expression of BOP1 and PES1 promotes ribosome biogenesis leading to abnormal proliferation of VSMCs and atherosclerosis." (PMID 36617563, 2023).
breast carcinoma (2 papers, 2021 to 2022). "Among these 12 CanCord34 genes, the knockdown of PUF60, EXOSC4, or BOP1 was accompanied by the loss of cell viability in breast cancer cell lines." (PMID 36497066, 2022). "To obtain evidence regarding the effects of serum factors on the expression of the CanCord34 genes, we examined the effects of serum starvation for 72 h on the levels of EEF1D, TIGD5, C8ORF73/MROH6, and BOP1 in the breast cancer SKBR-3, cervical cancer SiHa, and neuroblastoma IMR-32 cell lines." (PMID 36497066, 2022).
lymph node metastasis (2 papers, 2020 to 2022). "BOP1 expression in tissues of CRC patients was associated with TNM stage, lymph node metastasis, and distant metastasis (P < .05)." (PMID 32167616, 2020). "Furthermore, BOP1 expression in the tissues of CRC patients was associated with TNM stage, lymph node metastasis, and distant metastasis (P < .05)." (PMID 32167616, 2020).
rectal cancer (2 papers, 2008 to 2015). A primary or metastatic malignant neoplasm that affects the rectum. "We identified one well known CRC gene (SMAD2) and several other genes (EFNA1, BOP1, TGIF2 and STMN3) that possibly could be used for rectal cancer characterization." (PMID 18959792, 2008). "On basis of integrative analysis this study identified one well known CRC gene (SMAD2) and several other genes (EFNA1, BOP1, TGIF2 and STMN3) that possibly could be used for rectal cancer characterization." (PMID 18959792, 2008).
triple-negative breast carcinoma (2 papers, 2021 to 2022). An invasive breast carcinoma which is negative for expression of estrogen receptor (ER), progesterone receptor (PR), and human epidermal growth factor receptor 2 (HER2). "Whereas in vivo, BOP1 downregulation was reported to inhibit paclitaxel resistance and Cancer stem cells (CSC)-like phenotype in triple-negative breast cancer (TNBC) cells." (PMID 36203433, 2022).
acute myeloid leukemia (1 paper, 2021). Acute myeloid leukemia (AML) is a group of neoplasms arising from precursor cells committed to the myeloid cell-line differentiation. "However, compared with normal tissues, the levels of BOP1 were decreased in acute myeloid leukemia (LAML) and thyroid carcinoma (THCA) (P < 0.05)." (PMID 34603446, 2021).
Anophthalmia (1 paper, 2022). Absence of the globe or eyeball. "Additionally, previous studies showed that mutations in human OTX2 and RAX lead to anophthalmia, microphthalmia, and coloboma, findings that are in line with the eye phenotype upon bop1 knockdown in our study." (PMID 36007075, 2022).
Breast Invasive Carcinoma (1 paper, 2024). "In part two, we identify and validate expression and gene-related alterations of MYBL1, VCIP1, MYC and BOP1 genes in TNBC cell lines and patient samples selected from the Breast Invasive Carcinoma TCGA 2015 dataset available at cBioPortal.org." (PMID 38473786, 2024).
chronic myelogenous leukemia (1 paper, 2021). "Our results suggest that the expression level of BOP1 is highest in chronic myelogenous leukemia (LCML), while it is lower in most other tumor types." (PMID 34603446, 2021).
clear cell renal cell carcinoma (1 paper, 2021). "The results indicated that the expression of BOP1 protein in BRCA, clear cell renal cell carcinoma (ccRCC), COAD, LUAD, OV, and UCEC was significantly higher than that in corresponding normal tissues (P < 0.05), consistent with the results of BOP1 mRNA expression levels from TCGA." (PMID 34603446, 2021).
coloboma (1 paper, 2022). An abnormality in which a part of a structure in one or both eyes is missing. "In summary, bop1 knockdown led to a severe eye phenotype including microphthalmia, coloboma, and disturbed retinal lamination as well as defects in eye-specific marker gene expression during eye field induction and eye cell differentiation." (PMID 36007075, 2022). "In addition, we measured the angle of the eye fissure and observed a severe coloboma phenotype after bop1 MO injection but a normal phenotype after Control MO injection." (PMID 36007075, 2022).
colorectal tumor (1 paper, 2022). "BOP1 was found overexpressed in the colorectal tumor tissues and its expression level was related with copy number variation of MYC." (PMID 35222794, 2022).
gastric tumor (1 paper, 2022). "BOP1 was found up-regulated in gastric tumor tissues compared with paired normal tissues (P < 0.0001)." (PMID 35222794, 2022).
Hypertension (1 paper, 2015). The presence of chronic increased pressure in the systemic arterial system. "Remarkably, WDR12 overexpression consistently increased BOP1 in normal adult rat hearts (P<0.05), post-infarction (P<0.05), in Ang II-induced hypertension (P<0.05) and in vitro in neonatal rat cardiomyocytes (p = 0.061) and in cardiac fibroblasts." (PMID 25915632, 2015).
metastatic tumors (1 paper, 2022). "Thus, we suggest that targeting BOP1 and/or PLAU can be advantageous against both primary and metastatic tumors." (PMID 36203433, 2022).